GPR176 (G protein-coupled receptor 176)
Diseases named in the same sentence as GPR176 in open-access papers (continued):
Sharing a sentence is not in itself a finding about the gene and the disease.
tumor (8 papers, 2021 to 2025). "We conducted an in-depth investigation into the expression of GPR176 and its association with the tumor immune system in human cancers." (PMID 40689396, 2025). "GPR176 was strongly correlated with tumor-associated macrophages (TAMs) and M2 macrophage marker genes, suggesting its crucial role in the immune microenvironment of GC." (PMID 40689396, 2025). "The role of GPR176 in GC and its relationship with tumor immunity were further explored using cellular assays." (PMID 40689396, 2025). "We analyzed the StromalScore, ImmuneScore, and ESTIMATEScore of tumor samples with high and low GPR176 expression." (PMID 40689396, 2025). "In matched pair analysis, GPR176 expression was notably elevated in 32 tumor samples compared to adjacent normal gastric tissues." (PMID 40689396, 2025). "GPR176 expression in 249 pairs of CRC samples tended to increase in tumor tissues comparing with adjacent or normal tissues." (PMID 36905238, 2023). "Multivariate analysis showed that GPR176 (HR = 1.80, P = 0.003), residual tumor (HR = 2.81, P < 0.001), and age (HR = 1.55, P = 0.027) were independent prognostic factors for GC." (PMID 37291181, 2023). "To investigate the correlation between the expression level of GPR176 and the immune microenvironment, we analyzed the proportion of tumor immune cell subpopulations using the CIBERSORT algorithm and constructed a profile of 22 immune cell types in GC samples." (PMID 37291181, 2023). "Western blot analysis of GPR176‐KD cells and GPR176‐OE cells, as well as tumor tissues from Gpr176−CKO and WT Gpr176FL/FL mice, showed significant differences in the levels of key molecules involved the cell cycle and apoptosis." (PMID 36905238, 2023). "Then, we assessed the potential relationship between the expression levels of GPR176 and GC tumor-infiltrating immune cells using the TIMER database." (PMID 37291181, 2023). "We found that the high GPR176 expression group had higher stromal, immune, and ESTIMATE scores and lower tumor purity than the low GPR176 expression group." (PMID 37291181, 2023). "Furthermore, we analyzed the correlation between GPR176 and tumor immune infiltration and the possible response of patients with different GPR176 expression levels to immunotherapy." (PMID 37291181, 2023). "Additionally, we discovered that GPR176 regulates a variety of tumor and immune-related signaling pathways and can promote the proliferation, migration, and invasion of GC cells." (PMID 37291181, 2023). "It suggested that GPR176 plays a role in GC progression and tumor immunity." (PMID 37291181, 2023). "To determine whether GPR176 promotes tumor development, we constructed the Gpr176 conditional knockout (Gpr176−CKO) mice in the large intestine, the azoxymethane and dextran sodium sulfate (AOM‐DSS) mice model was further established." (PMID 36905238, 2023). "In both Gpr176−CKO mice model and the subcutaneous tumor model, loss of GPR176 significantly diminished BNIP3L phosphorylation, while a slight alteration in PINK1 phosphorylation level was observed, suggesting that GPR176 mainly modulated BNIP3L phosphorylation both in vitro and in vivo." (PMID 36905238, 2023). "Interestingly, GPR176 induced the conversion of TIM while reducing the tumor immune burden (TMB)." (PMID 37124060, 2023). "Second, lack of in vivo xenograft tumor experiments to validate the relationship between GPR176 and cellular biological behavior." (PMID 40689396, 2025). "In addition, the Spearman correlation analysis showed that GPR176 expression levels were significantly positively correlated with stromal, immune, and ESTIMATE scores and negatively correlated with tumor purity." (PMID 37291181, 2023). "Moreover, GPR176 may influence the immune status of the tumor microenvironment in STAD by regulating the immunosuppressive function of TGFB1 and the chemotactic activity of CXCL12, further affecting tumor progression." (PMID 40689396, 2025).
tumor (continued). "The results showed that the high GPR176 expression group had a higher TIDE score, T-cell dysfunction score, T-cell exclusion score, and lower MSI score, suggesting that the high GPR176 expression group may have a higher rate of tumor immune escape and less effective after receiving immunotherapy." (PMID 37291181, 2023).
cancer (7 papers, 2021 to 2025). A tumor composed of atypical neoplastic, often pleomorphic cells that invade other tissues. "In terms of the KM Plotter database, GPR176 mRNA was positively associated with a higher overall survival (OS) rate in all, male and Asian oesophageal squamous carcinoma patients (p < 0.05), and in cancer patients of Grade 2 with a high or low mutation burden." (PMID 37584712, 2023). "Kaplan–Meier Plotter showed that GPR176 mRNA expression was positively correlated with the relapse-free survival (RFS) of all cancer patients (p < 0.05) and the overall survival (OS) of PR (progesterone receptor)-positive cases (p < 0.05)." (PMID 37079213, 2023). "Given that the role of GRP176 in tumors is unclear, we first evaluated the GPR176 expression levels in pan-cancer tissues." (PMID 37124060, 2023). "Based on these results, we hypothesize that the overexpression of GPR176 might exert a suppressive effect on cancer progression by modulating the activity of immune-stimulating factors, such as ENTPD1." (PMID 40689396, 2025). "GPR176 is a member of the GPCRs family and has been rarely studied in cancer." (PMID 37291181, 2023). "To further explore the diagnostic value of GPR176 in GC, we analyzed the expression levels of GPR176 in the TCGA STAD database and found that it was significantly higher in GC tissues (n = 373) than in adjacent normal tissues of cancer (n = 32; P < 0.001)." (PMID 37291181, 2023). "However, the function and role of GPR176 in malignant tumors are unknown, especially in TIM." (PMID 37124060, 2023). "There was a negative relationship between GPR176 mRNA expression and OS or post-progression survival of the cancer patients with lymph node involvement (p < 0.05)." (PMID 37079213, 2023). "Surprisingly, a negative relationship between GPR176 mRNA expression and OS, PPS, or DMFS was seen in the cancer patients with lymph node involvement or ER positivity, which might be linked to the post-surgery treatment, including endocrine and radiological therapies." (PMID 37079213, 2023).
GPR176 also shares sentences with these, for which no sentence is quoted: head and neck squamous cell carcinoma (2 papers); uterine corpus endometrial carcinoma (2); amyotrophic lateral sclerosis (1); cholangiocarcinoma (1); colon adenocarcinoma (1); coronary artery disease (1); endometrial cancer (1); glioblastoma multiforme (1); Glucose intolerance (1); hepatocellular carcinoma (1); invasive breast carcinoma (1); kidney chromophobe (1); lymph node metastasis (1); Obesity (1); pancreatic adenocarcinoma (1); paraganglioma (1); pheochromocytoma (1).